TMEM31 (transmembrane protein 31)
Synonyms: MGC39655
Tractability: Antibody: UniProt predicts a signal peptide or a membrane-spanning region. PROTAC: ubiquitination databases record sites on it.
Gene: Protein-coding gene on chromosome X (103,710,909 to 103,714,036, forward strand). Ensembl gene ENSG00000179363.
Subcellular location: Membrane
Subcellular location (Human Protein Atlas): Nucleoli fibrillar center
Gene Ontology:
Molecular function: protein binding
Cellular component: membrane
Homologues: Orthologues: chimpanzee TMEM31 (100% identical), macaque TMEM31 (92% identical), dog TMEM31 (58% identical), pig TMEM31 (58% identical).
Diseases named in the same sentence as TMEM31 in open-access papers:
TMEM31 is named in the same sentence as 5 diseases in open-access papers, as found by Europe PMC text mining. Sharing a sentence is not in itself a finding about the gene and the disease. The quoted sentences say what the papers report.
metastatic melanoma (2 papers, 2019 to 2023). A melanoma that has spread from its primary site to another anatomic site. "Surprisingly, the expression of TMEM31 was found significantly increased in metastatic melanomas compared to in primary tumors." (PMID 37860520, 2023). "Examples include PASD1 in AML, LY6K in lung and oesophageal carcinomas, sperm protein 17 (Sp17) in head and neck squamous cell carcinoma and transmembrane protein 31 (TMEM31) in metastatic melanoma." (PMID 30678059, 2019).
melanoma (1 paper, 2023). A malignant, usually aggressive tumor composed of atypical, neoplastic melanocytes. "The expression characteristics of TMEM31 was investigated by comparing the level of TMEM31 in primary melanomas and metastatic ones." (PMID 37860520, 2023). "As a newly discovered biomarker, little is known about the biological role and mechanism of TMEM31 in melanoma as well as other malignancies." (PMID 37860520, 2023).
cancer (1 paper, 2024). A tumor composed of atypical neoplastic, often pleomorphic cells that invade other tissues. "Brother of the regulator of imprinted sites (BORIS), acrosin binding protein (ACRBP), synaptonemal complex protein 1 (SYCP1), and transmembrane protein 31 (TMEM31) cancer/testis antigens have utilized for in silico peptide vaccine design due to their high expression in various tumors." (PMID 38923980, 2024). "NY-SAR-35 antigen, previously unexplored in bioinformatics, shares characteristics with BORIS, TMEM31, ACRBP, and SYCP1 in terms of its high expression on the cancer cells, notable immunogenicity, and absence of expression on the normal cells." (PMID 38923980, 2024).
tumor (1 paper, 2023). "Altogether, TMEM31 might play critical role in the process of tumor metastasis." (PMID 37860520, 2023).
TMEM31 also shares sentences with these, for which no sentence is quoted: head and neck squamous cell carcinoma (1 paper).